IL6 (interleukin 6)
Diseases named in the same sentence as IL6 in open-access papers (continued):
Sharing a sentence is not in itself a finding about the gene and the disease.
COVID-19 (continued). "Since platelets contribute to the cytokine storm observed in severe COVID-19, anti-inflammatory agents like corticosteroids (e.g. dexamethasone) and interleukin-6 (IL-6) inhibitors (e.g. tocilizumab) have been used to manage the excessive inflammation." (PMID 39118706, 2024). "Several studies have reported that IL-6 is the cytokine that is most often significantly increased in severe/critical cases compared to mild/moderate cases of COVID-19 in both adults and children." (PMID 39596272, 2024). "The COVID-19 EVs group had increased levels of IL-1β, IL-6, and TNF-α compared to the other two groups." (PMID 39475319, 2024). "It is evident that increased circulating IL-10, IL-6, IFN-gamma-inducible protein 10 (IP-10), and monocyte chemoattractant protein-1 and -3 (MCP-1 and MCP-3) are significantly associated with COVID-19 severity." (PMID 39633683, 2024). "The ELF concentrations of IL-6, IL-8, IL-17A, IL-25, and IL-31 were significantly increased in COVID-19 patients." (PMID 38654351, 2024). "Among others, IL-6 is a key player in this cytokine response with significantly elevated circulating levels in the plasma of patients with COVID-19, and consequently it has been reported to contribute to the related vascular pathology." (PMID 38745756, 2024). "This influx of proteins can lead to increased severity in hospitalized COVID-19 patients, associated with high systemic levels of IL-6 β, TNF-α, and IL-6." (PMID 39599792, 2024). "Among these, IL-1β as well as IL-6 emerged as particularly significant markers, especially in long COVID-19 patients, pointing towards their key role in driving persistent inflammation and ongoing symptoms following the acute phase of infection." (PMID 39518964, 2024). "In a cohort study with 35 neuroCOVID-19 patients, elevated levels of interleukin-6 (IL-6) in the CSF were correlated with COVID-19 severity." (PMID 39205221, 2024). "Elaborated studies on other cytokines, IL-6 and INF gamma, and their correlation/association to COVID-19 clinical outcomes need to be done." (PMID 38287362, 2024). "Elevated IL-6 levels have been observed in patients with severe disease states, not only in COVID-19 but also in conditions characterized by systemic inflammation, where IL-6 inhibition is beneficial." (PMID 39203987, 2024). "Among the pro-inflammatory cytokines observed in COVID-19 patients, interleukin-6 (IL-6), interleukin-1-beta (IL-1β), interferon-gamma (IFN-γ) and tumor necrosis factor-alpha (TNF-α) are generally associated with illness progression." (PMID 39199315, 2024). "It is widely acknowledged that severe COVID-19 is characterized by immune dysregulation, with IL-6 playing a central role as a key regulator of adaptive immunity." (PMID 39040601, 2024). "In order to test the potential impact of RIC in the setting of COVID-19, we selected a panel of pro-inflammatory cytokines that included IL-6, TNF-α, IL-1β, and IFN-γ." (PMID 36445625, 2024). "The early anti-inflammatory treatments to inactivate cytokine functions (mainly anti-interleukin-1 and anti-interleukin-6 compounds) contribute to the improvement of the prognosis of COVID-19." (PMID 38474248, 2024). "The signaling pathway was proposed based on the predominant finding of elevated IL-6 levels observed in critically ill COVID-19 patients." (PMID 38694122, 2024). "Increased pro-inflammatory cytokines, such as IL-6 and TNF-α, have been observed in adults with severe COVID-19 and are significantly associated with mortality." (PMID 38398867, 2024). "For example, miR-451a is an IL-6R translational repressor that exacerbates the IL-6-induced cytokine storm and one of the top five downregulated microRNA genes in COVID-19 patients." (PMID 38932387, 2024). "Evidence has shown the presence of significantly elevated levels of IL-6 in individuals diagnosed with COVID-19." (PMID 37742314, 2024).
COVID-19 (continued). "Age and inflammation (IL-6, a marker of COVID-19 severity), as well as glycolytic enzymes (enolase–ENO1), also ranked amongst the top correlates to d-dimer measurements." (PMID 38543504, 2024). "Fibrinolysis increases during COVID-19 due to elevated IL-6 levels, and it has been reported that IL-6 levels are associated with high levels of fibrinogen (F1)." (PMID 39885991, 2024). "In particular, altered cardiac rhythm and conduction emerged in patients affected by COVID-19 acutely or subacutely, a condition where the so-called “cytokine storm” with high IL6 levels also plays a relevant role as a predictor of adverse outcome." (PMID 39596280, 2024). "In COVID-19 patients with cardiovascular disease, fibrinogen and IL6 levels positively correlated (r = 0.851, p = 0.000)." (PMID 38474287, 2024). "This study aimed to evaluate the association of the levels of cytokines interleukin (IL)-2, IL-6, tumor necrosis factor-alpha (TNF-α), interferon-gamma (IFN-γ), and IL-10 with the severity of COVID-19 in Bangladesh." (PMID 38707035, 2024). "IL-6 displayed also a longitudinal value, showing a significative decrease in COVID-19-positive patients over time." (PMID 39582872, 2024). "Hamster studies have showed that COVID-19 leads to IL-1β and IL-6 expression within the hippocampus and medulla oblongata and is associated with decreased neurogenesis in the hippocampal dentate gyrus which leads to learning and memory deficits." (PMID 39474424, 2024). "The so-called cytokine storm in severe COVID-19 is mediated by an exponential increase in the levels of inflammatory cytokines such as interleukin-6 (IL-6) and tumor necrosis factor-alpha (TNF-α)." (PMID 38384612, 2024). "Proinflammatory TH1-related cytokines (IP-10 and MIP-1a) and ARDS-associated cytokines (IL-6, IL-8, IL-1ra, and MCP-1) showed positive correlations with the severity of COVID-19." (PMID 38779486, 2024). "SIADH has also been increasingly reported in patients with COVID-19, as well, ascribing this phenomenon to IL-6 and other mechanisms, such as pneumonia-associated ADH release and baroceptor-mediated ADH release in hypovolemic and hypotensive COVID-19 patients." (PMID 38761322, 2024). "As the first Mendelian randomization study examining the four key IL-6 pathway components together, we found evidence for the protective effect of higher baseline IL-6 levels against developing severe COVID-19." (PMID 39062668, 2024). "Considering that ORF3a stimulates NF-κB to induce cytokine production such as TNFα and IL-6, and that elevation of TNFα and IL-6 are two strong and independent survival predictors of patients with COVID-19, targeting these cytokines is also appealing." (PMID 38251382, 2024). "A study of COVID-19 patients with neurological disease observed elevated proinflammatory cytokines, including IL-6, IL-8 and IL-18 in serum andCSF, while another study reported elevated IL-6, IL-8 and TNF-α in CSF." (PMID 38995681, 2024). "Several cytokines were elevated in COVID-19 patients with a dramatic increase in disease severity such as GM-CSF and IL-6." (PMID 38855114, 2024). "Among the various cytokines being considered for the improvement of COVID-19, interleukin-6 (IL-6) often emerges as the most significant." (PMID 38694803, 2024). "While further limited by the small number of PLWH with severe illness, interaction models also suggested that higher concentrations of IFN-α2, IL-6, CCL3, IL-1a, and IL-1Ra were associated with more severe COVID-19 in PLWH." (PMID 38368384, 2024). "These molecules modulate CS in COVID-19, notably meloxicam, which exhibited a downregulatory effect on cytokines (IL-6, CCL2, GM-CSF, CXCL10, IL-2, and TNF-α)." (PMID 39518964, 2024). "The results of present study showed that high level of IL-6 at baseline is a strong predictor for ACS development in COVID-19 patients." (PMID 39395941, 2024).
COVID-19 (continued). "In COVID-19 patients, the immune response to the viral infection can lead to elevated levels of serum cytokines, including Interleukin-6 and Tumor necrosis factor." (PMID 38616997, 2024). "The principal pathophysiology of musculoskeletal manifestations related to COVID-19 includes cytokine storm, high expression of IL-6 and other proinflammatory mediators, development of a prothrombotic state, and autoimmunity." (PMID 38186417, 2023). "Another publication stated that TTN is downregulated after IL-6 treatment, implying a corresponding downregulation in patients with COVID-19." (PMID 37109540, 2023). "Elevated levels of both IL-1 and IL-6 have been observed in individuals with severe cases of COVID-19 and are thought to contribute to the hyperinflammatory response seen in these patients." (PMID 37046952, 2023). "Meanwhile, another study also advocated for the use of glucocorticoids during severe COVID-19, claiming that the drug suppresses IL-6 levels." (PMID 37109050, 2023). "On the contrary, a small and significant increase in plasma concentration of IL-6 was observed at long-term after COVID-19 recovery (2.9 (1.3 – 5.2) pg/mL) compared to 3 months after COVID-19 recovery (1.7 (1.0 - 3.1) pg/mL)." (PMID 37868959, 2023). "We designed a systematic review and meta-analysis to explore correlates of IL-6 levels and long COVID-19 for future trials targeting this immune mediator." (PMID 37095536, 2023). "Analysis of COVID-19 patients revealed heightened serum levels of IL-1β and IL-6, suggesting a pivotal role of these cytokines in the systemic inflammatory response associated with the disease." (PMID 37986089, 2023). "According to the role of IL6 in the complex COVID-19 pathogenesis, involving not only a deregulated inflammatory and immune response, but also a prothrombotic milieu, this cytokine has also been investigated as a promising therapeutic target." (PMID 37108262, 2023). "We confirmed these results in a monocentric prospective observational study conducted at Siena University Hospital in which the prognostic value of MR-proADM was compared for the first time with other COVID-19 markers of lung damage, including KL-6 and IL-6." (PMID 37371775, 2023). "In this context, polymorphisms at IL6, IL6R, and IL6ST genes become interesting candidates to be prognostic and predictive markers of COVID-19 severity." (PMID 37243282, 2023). "In the latest prospective, randomized controlled pilot study to date, 24 COVID-19 patients with refractory shock, hypercytokinemia (defined as IL-6 ≥500 ng/L), and indication for RRT or ECMO were enrolled." (PMID 36817416, 2023). "Compared to other prognostic parameters for COVID-19, such as interleukin-6, D-dimers, C-reactive protein, and erythrocyte sedimentation rate, NLR is more practical for clinical application since it can easily be obtained via routine blood examinations." (PMID 37101265, 2023). "Interleukin-6 has been recognized as a major role player in COVID-19 severity, being an important regulator of the cytokine storm." (PMID 37243282, 2023). "In the meta-analysis of clinical trials of patients hospitalized for COVID-19, administration of IL-6 antagonists, compared with placebo or usual care, was associated with lower 28-day all-cause mortality." (PMID 37901822, 2023). "The potential for the hyperactivation of IL-6 in the host immune pathway contributes to the development of long-term symptoms of COVID-19." (PMID 37095536, 2023). "IL-6 levels are elevated in COVID-19 patients, peak in critically ill patients, and gradually increase with disease severity." (PMID 37310657, 2023). "Various studies have studied the possibility of utilizing IL-6 inhibitors to treat COVID-19, as they can lessen cytokine release syndrome (CRS) and reduce the load of the virus." (PMID 37958192, 2023).
COVID-19 (continued). "Among the severe/critical COVID-19 patients, significantly higher levels of IL-6 were also observed in blood samples obtained at the time of hospital admission compared with those obtained at the time of discharge (0.9 pg/mL, IQR 0.3-1.3 pg/mL, p <0.001)." (PMID 36810114, 2023). "Through clinical sample verification, the level of IL6 in COVID-19 patients with myocardial injury increased, whereas lymphocyte subsets decreased." (PMID 37564653, 2023). "The hsTnI levels in COVID-19 patients with high IL6 levels were higher than those in patients with low IL6 (P<0.05)." (PMID 37564653, 2023). "It has also been reported that the levels of inflammatory markers, including IL-6, are increased in patients with COVID-19." (PMID 36711294, 2023). "From the start of the pandemic, the understanding of the role of IL-6 in the management and treatment of COVID-19 patients improved progressively." (PMID 37363429, 2023). "COVID-19 patients treated with Tranilast had apparently lower levels of proinflammatory cytokines (e.g., IL-1β, IL-6 and TNF-α) than the controls." (PMID 37251383, 2023). "IL-6 is considered to be one of the potential biomarkers of COVID-19 progression, and is a very important guideline for patient progression, treatment, and prognosis assessment." (PMID 38018195, 2023). "Apart from these findings, it should be noted that IL-6 was the single cytokine that consistently increased in COVID-19 and was also used as a marker to distinguish levels of COVID-19 severity." (PMID 37106750, 2023). "As shown inTable 3, more patients with mild COVID-19 (n = 43, 75.44%) had IL-6 levels below the cut-off compared with those (n = 14, 24.56%) who had levels above the cut-off." (PMID 38099004, 2023). "Similar to our study, non-survivor patients with COVID-19 infection had significantly higher IL-6 and IL-10 concentrations compared to survivor patients with COVID-19 on hospital admission." (PMID 36766961, 2023). "Among them, we can highlight the involvement of slc2a1a, slc2a1b (cell membrane glucose transport), interleukins- il1b, and il6 (pro-inflammatory pathway), nfkbiab, and coa1 (mitochondrial respiratory chain) in COVID-19." (PMID 37047078, 2023). "We can cite, as an example, the high levels of C-reactive protein, a protein whose expression is driven by IL-6, as also a biomarker of severe clinical manifestations of COVID-19." (PMID 37515295, 2023). "For example, Atlizumab is an immunosuppressive drug and anti-IL6, and it is considered an off-label treatment for those with COVID-19-related acute respiratory distress syndrome." (PMID 37158893, 2023). "The elevated inflammatory markers CRP, IL-6, and D-dimer in most of the COVID-19-infected individuals support the inflammatory "cytokine storm" response theory and hypercoagulation status in severe COVID-19-infected individuals." (PMID 38313184, 2023). "IFN γ and IL-6 were chosen as indicators of immune activation as they are also associated with poor outcome in ARDS and COVID-19." (PMID 36927455, 2023). "Every IL-6 CSF/serum ratio in every COVID-19 patient was between 0.15–0.55 indicating an IL-6 origin from blood invading the CSF compartment." (PMID 36759861, 2023). "Increased levels of IL-6, IL-13, YKL-40, and KL-6 were associated with mortality in COVID-19 patients." (PMID 36975498, 2023). "Early into the pandemic, those diagnosed with COVID-19 were found to display significantly elevated proinflammatory responses, including increased levels of IL-6, TNF, IL-2, IL-1β, IP-10, IFNγ, MCP1 and MIP1α." (PMID 37091818, 2023). "Microbe-mediated amino acids were positively associated with increased levels of inflammatory cytokines (CXCL9, CXCL10, IFN-γ and IL-6) and negatively correlated with decreased levels of cytokines (IL-9 and IL-17) in COVID-19." (PMID 37205106, 2023). "The cytokine storm of COVID-19 patients (with an elevation of IL-1β, IL-6 and TNF-α) has been related to the increase of eicosanoids including AA and its metabolites." (PMID 36984782, 2023).
COVID-19 (continued). "In summary, the present study demonstrates the increase in nasopharyngeal MPO, ADA, CCL22, TNFα, and IL-6 mRNA expression in COVID-19 patients." (PMID 36482706, 2023). "Antibodies targeting IL-6 or GM-CSF, such as tocilizumab, sarilumab, gimsilumab, and lenzilumab, are approved or under clinical investigations to treat severe COVID-19 patients." (PMID 37021053, 2023). "In contrast, in other severe infections, such as COVID-19, randomized trials have suggested that IL-6 is critical for pathogenesis, with evidence that blockade of IL-6 improves survival." (PMID 36801374, 2023). "Various studies have suggested that proinflammatory cytokines (mainly IL-6) are responsible for the acute lung injury seen in COVID-19." (PMID 37834324, 2023). "We detected increased IL-6 levels in COVID-19 male patients at diagnosis, which remained elevated in the post-COVID-19 patients for up to 5 months." (PMID 37896963, 2023). "In this study, we found that patients with critical COVID-19 can be classified by two distinctive groups in terms of cytokinemia and T-cell activation levels, according to their levels of serum IL-6." (PMID 37081872, 2023). "It is evident that multiple inflammatory cytokines, including TNF-α, IL-1β, IL-6, and IL-10 play a significant role in the pathogenesis of COVID-19 induced morbidity and mortality." (PMID 37033622, 2023). "As the variations in MBL levels were greater in the group of patients with severe acute COVID-19, the levels of the cytokines IL-6 and TNF-α were evaluated in relation to this form of the disease." (PMID 37138871, 2023). "The determination of a panel of proinflammatory cytokines in serum samples from P10 outside clinical events (n = 2) and during mild COVID-19 (n = 1, 4 days from symptom onset) showed an increase in IL-6 levels during infection." (PMID 36976641, 2023). "Almost all of the study population (94%) had IL-6 levels over 43.5, indicating severe COVID-19, whereas 29.8% had IL-6 levels below 43.5, indicating non severe COVID-19." (PMID 37960722, 2023). "Most severe cases of COVID-19 with respiratory distress syndrome were associated with high systemic levels of IL-1β, TNF-α, and IL-6." (PMID 37112918, 2023). "On the other hand, dysregulated cytokine responses, most notably fluctuations of serum IL-6 during COVID-19, have also been established in the literature." (PMID 37568402, 2023). "Each unit increase in serum IL-6 levels would increase the odds of severe COVID-19 by 1.075 (P = 0.033, 95% confidence interval: 1.006 – 1.148)." (PMID 37568161, 2023). "The cytokine profile of the inflammatory cascade in SARS-CoV-2 was well defined, with concentrations of TNF-α, IL-6 and IL-10 distinctly mediating the cytokine storm and clearly differentiating mild from severe cases of COVID-19." (PMID 37759873, 2023). "This underscores the importance of serum calcium as a potential early-stage biomarker for assessing COVID-19 severity, linking it to multiorgan injuries and elevated levels of pro-inflammatory cytokines like IL-6." (PMID 38203589, 2023). "Inflammation, particularly represented by high IL-6 levels, seems to be a fundamental factor in the pathogenesis of COVID-19, as confirmed by our study." (PMID 36675242, 2023). "More specifically, patients with higher IL-6 serum levels had a two-fold increase in the manifestation of post-COVID-19 vertigo (V+)." (PMID 36942191, 2023). "In the severe COVID-19 group, we observed a hyperinflammatory state, as judged by increased concentration of cytokines (IL-1α, IL-4, IL-6, IL-10 and IL-17A), chemokines (IP-10 and MIP-1β), and adhesion markers (E-selectin and ICAM-1)." (PMID 37441066, 2023). "STAT3 is a key transcription factor for harmful IL-6 that stimulates transforming growth factor-1beta, which plays a crucial role in pulmonary fibrosis in COVID-19 acute lung injury." (PMID 37021053, 2023). "For instance, we found enrichment of JAK-STAT signaling, IL-4 signaling, and IL-6 signaling in COVID-19 patients." (PMID 36992700, 2023).